TLR2 (toll like receptor 2)
Diseases named in the same sentence as TLR2 in open-access papers (continued):
Sharing a sentence is not in itself a finding about the gene and the disease.
type 1 diabetes (22 papers, 2013 to 2023). "The gene polymorphism of TLR2 has been investigated in autoimmune diseases such as psoriasis vulgaris and type I diabetes." (PMID 37176151, 2023). "Similarly, TLR2 polymorphisms have been associated with an increased susceptibility to autoimmune diseases, such as type 1 diabetes (T1D)." (PMID 37998389, 2023). "In Type 1 diabetes, increased TLR-2 and TLR-4 expression was found in T1D patients and associated with increased NF-κB expression and IL-1β release." (PMID 36688057, 2022). "It was then demonstrated that TLR2 signaling improves immunoregulation and prevents type 1 diabetes." (PMID 34830017, 2021). "The conducted analysis showed that the percentage of CD8+ TLR2+ lymphocytes in the peripheral blood of children with type 1 diabetes was lower than in the control group (p = 0.026)." (PMID 34830017, 2021). "GSEA analysis indicates that the high expression groups of ALDH2, C5AR1, CFOS, IL1B, TLR2, TRXR1 jointly participate in the pathways of viral myocarditis, VEGF signaling pathway and type I diabetes mellitus associated with MI." (PMID 34799616, 2021). "The STAT3 was detected in the TLR2-positive glomeruli in the STZ-induced type 1 diabetic mice and in the diabetic mice administered Pg-LPS." (PMID 29018490, 2017). "Furthermore, it was shown that the deletion of PKCδ in pancreatic islets protects from cytokine-induced apoptosis, NO generation, and also disrupts toll-like receptor 2 (TLR2) signaling, which activation contributes to the development of type 1 diabetes." (PMID 32466765, 2020). "Recent findings have shown increased TLR-2 and −4 expression, signaling, ligands, and functional activation both in type 1 diabetes mellitus (T1DM) subjects and in monocytes of type 2 diabetic (T2DM) patients." (PMID 23506673, 2013). "The increase of lymphocytes expressing TLR2 and TLR4 receptors in patients’ cases with type 1 diabetes in the early stage of the disease and those treated chronically suggests that stimulation of these receptors accompanies the development of the disease." (PMID 34830017, 2021). "Another example of desensitization is the prevention of type 1 diabetes in NOD mice by TLR2 ligands, called “TLR2 tolerance”." (PMID 33584703, 2020). "In addition, clinical data indicate that in patients with type 1 diabetes, ligands, endotoxins, heat shock proteins 60 (Hsp60), and high mobility groups 1 (HMGB1) of both TLR2 and TLR4 are increased." (PMID 32933213, 2020). "Expression of TLR2 was very limited in the non-diabetic mice and the non-diabetic mice administered Pg-LPS, but was present in STZ-induced type 1 diabetic mouse glomeruli." (PMID 29018490, 2017).
leukemia (21 papers, 2010 to 2025). A malignant (clonal) hematologic disorder, involving hematopoietic stem cells and characterized by the presence of primitive or atypical myeloid or lymphoid cells in the bone marrow and the blood. "To assess TLR function in leukemia cells, we measured in vitro responses of mouse cells to the TLR2 agonist, PAM3CSK4." (PMID 40111422, 2025). "AVR-121 and AVR-123 are novel classes of small-molecule dual inhibitors of TLR2/4 tested in a human leukemia monocytic cell line (THP-1) and cord-blood-derived mononuclear cells (CBMCs)." (PMID 39195259, 2024). "In summary, the present study identifies that d-pep-P6 can selectively induce the differentiation of both human leukemia cell lines and primary human leukemia cells by activating TLR-2 signaling." (PMID 38272890, 2024). "Further mechanism study suggested that d-pep-P6 induced human leukemia cell differentiation by directly activating a TLR-2 signaling pathway." (PMID 38272890, 2024). "The activation of TLR2, a canonical costimulatory receptor, promotes the regression of established leukemia." (PMID 29458388, 2018). "The study confirms sTLR2 production is increased by activation of peripheral monocytes and a monocytic-leukemia derived cell line with Pam3CSK4 suggesting that TLR2 activation increases its own shedding." (PMID 25531754, 2014). "RT-PCR was performed to detect TLR-2 expression of leukemia cells." (PMID 38272890, 2024). "Mechanistically, we found that l- and d-pep-P6 could induce differentiation of human leukemia cell lines and primary human leukemia cells by triggering TLR-2 signaling." (PMID 38272890, 2024). "Although the association between the expression of TLR2 and the pathogenesis of leukemia has not yet been established." (PMID 30196472, 2019). "Thus, it can be argued that products derived from apoptotic leukemia cells may have TLR2 inducing properties and may, therefore, stimulate the production of pro-inflammatory cytokines." (PMID 30196472, 2019). "These 1928zT2 T cells not only could eradicate the CD19-expressing NALM6 cells and K562 cells specifically and potently in vitro, they could significantly promote the remission of NALM-6 subcutaneous tumors ex vivo, indicating the TLR2 incorporation enhanced the anti-leukemia effects of CAR T cells." (PMID 29458388, 2018). "Epinecidin-1 peptide also has been found to regulate the toll-like receptor (TLR)-2/MyD88 pathway in RAW264.7 macrophage and exert anticancer activity for leukemia U937 cells." (PMID 30915150, 2019). "There are few reports regarding the potential roles of TLR2 and TLR4 in the pathogenesis of leukemia." (PMID 30774831, 2018). "Tp92 mediated the human monocytic cell line derived from an acute monicytic leukemia patient (THP‐1) cell death by recognizing CD14 and/or TLR2 on cell surfaces." (PMID 30596396, 2018). "Furthermore, augmented TLR2 signaling is associated with myelodysplastic syndrome, an HSC disorder characterized by ineffective hematopoiesis and a high risk of transformation to leukemia, suggesting that aberrant signaling through this receptor may have clinically significant effects on HSCs." (PMID 27315114, 2016). "By this, findings on chemotherapy-induced EV miRNAs in leukaemia are rare at present, but bone marrow microenvironment stromal cells have been reported to downregulate miR-23a-5p levels in AML cells to protect them from the chemotherapy-induced apoptosis targeting Toll-like receptor 2 expression." (PMID 39325141, 2025). "Moreover, TLR2 stimulation with the natural polysaccharide from medicinal mushroom Trametes versicolor, activates human NK cells, inducing IFN-γ secretion and the lysis of K562 leukaemia cells." (PMID 36499361, 2022). "In this study, the NK cells from peripheral blood of patients with leukemia show a significant decrease in the expression of TLR1, but not of TLR2." (PMID 34567117, 2021).
Nephropathy (21 papers, 2009 to 2025). A nonspecific term referring to disease or damage of the kidneys. "The disease is characterised by kidney damage, caused by the binding of LipL32 to toll-like receptor 2, which triggers an inflammatory cascade." (PMID 39728812, 2024). "To explore this possibility further, we studied the progression of two models of kidney disease in mice deficient in TLR-2, TLR-4 and MyD88." (PMID 23844229, 2013). "The activation of TLR2 in macrophages triggers a proinflammatory response that contributes to nephropathy in diabetic mice." (PMID 40362229, 2025). "In summary, our findings highlight TLR2 as a key regulatory factor in Pb‐induced kidney damage and suggest that BGM protects renal tissues by targeting the TLR2/NF‐κB signaling pathway." (PMID 41221091, 2025). "Given the extensive inhibitory effect of sTLR2 on nephropathy-induced vascular pathology observed here, the involvement of specific TLR2 and/or TLR4 DAMP agonists were investigated." (PMID 37849759, 2023). "TLRs have been implicated in various renal diseases, including ischemia-reperfusion injury (IRI), wherein endogenous TLR2 and TLR4 ligands are thought to be released from the renal epithelium." (PMID 38015955, 2023). "Activation of macrophage TLR2 induces a pro-inflammatory response and pathogenesis of nephropathy in diabetic mice and inhibition of macrophage TLR2 signaling leads to suppressed diabetic nephropathy." (PMID 32660446, 2020). "Because TLRs have been implicated as effectors in kidney diseases and TREM-1 has been previously linked to TLR signaling, we investigated TLR-2 and TLR-4 as putative receptors for kidney DAMPs and macrophage activation." (PMID 23844229, 2013). "However, based on studies on the role of Toll-like receptors in nephropathy induced by a Toxoplasma gondii infection, it was found that mainly TLR2 plays a role in kidney protection against T. gondii infection." (PMID 32958053, 2020). "Proteinuria has been associated with TLR2 activation in the kidneys, leading to inflammation in albumin-overloaded nephropathy rats and patients with non-IgA mesangioproliferative glomerulonephritis." (PMID 32079183, 2020). "We chose TLR2 ligands because it was reported that linc0949 and linc0597 were regulated in THP-1 macrophages following Pam3CSK4 stimulation and TLR2 was required for the production of prototypical lupus autoantibodies and the development of renal disease in murine lupus." (PMID 25994030, 2015). "The top-ranked item by betweenness centrality, not only established the linkage between TLR2 and kidney diseases but also confirmed that TLR2 might participate in ischemia-reperfusion via both MyD88-dependent and MyD88-independent pathways in the pathogenesis of acute ischemic kidney injury." (PMID 40584714, 2025). "In this study, TLR2 expression was increased in the ADR-induced nephropathy model, while Remodelin and NAT10 siRNA treatment reduced TLR2 levels." (PMID 40108127, 2025). "Recent studies demonstrated that overexpression of TLR2 and TLR4 has a crucial role in facilitating kidney damage after renal I/R." (PMID 35911649, 2022). "In conclusion, the results would suggest that both TLR2 and TLR4 have the relevance to the promotion of P. gingivalis-induced nephropathy." (PMID 29018490, 2017). "TLR2 does not play an essential role in the development of renal fibrosis or the progression of renal disease after UUO-injury." (PMID 19479087, 2009).
ovarian carcinoma (21 papers, 2012 to 2025). A malignant neoplasm originating from the surface ovarian epithelium. "The activation of TLR2, 4, and 5 culminate in the activation of inflammation-associated cytokine signaling pathways in ovarian cancer and the adjacent tissues, leading to the activation of NF-kappa B signaling." (PMID 33794773, 2021). "Our research sheds light on the prognostic potential of TLR2 in developing new diagnostic approaches and thus in increasing survival in patients with confirmed ovarian cancer." (PMID 34439871, 2021). "For example, hypoxia-conditioned tumor sEVs carrying miR-1225-5p affect macrophage polarization through Toll-like receptor 2, thereby enhancing ovarian cancer’s progression." (PMID 40008006, 2025). "The results confirmed that SAA1 released from ovarian cancer cells indeed promotes the recruitment and activation of MDSCs through its interaction with TLR2/4 on the surface of MDSCs." (PMID 41029721, 2025). "These experiments confirm that SAA1 released by ovarian cancer cells acts on TLR2/4 on the surface of MDSCs, thereby promoting MDSCs recruitment and the differentiation of GMPs into MDSCs." (PMID 41029721, 2025). "The studies aimed at demonstrating the usefulness of TLR2 as a biomarker in the advanced stage of ovarian cancer." (PMID 34439871, 2021). "In the present study, we assessed TLR2 expression in blood samples from ovarian cancer patients with various stages of FIGO." (PMID 34439871, 2021). "The main aim of our research was to recognize the molecular mechanism of ovarian cancer cells action on autologous neutrophils in respect to the interaction of HspA1A with TLR2/4." (PMID 22528050, 2012). "Similarly, in ovarian cancer, overexpression of the mirtron hsa-mir-1225–5p facilitates M2 macrophage accumulation by directly targeting toll-like receptor 2 (TLR2)." (PMID 40861257, 2025). "It occurred in the present study that patients with OC are characterized with an elevated level of TLR2 in comparison to healthy individuals, suggesting that TLR2 may serve as a promising non-invasive biomarker of ovarian cancer." (PMID 34439871, 2021). "Pattern recognition receptors TLR2, 4, and 5 respond to bacterial flagellin or LPS and have pivotal roles in driving inflammation in ovarian cancer." (PMID 33794773, 2021). "On the other hand, studies showed that TLR2 expressed on the surface of epithelial ovarian cancer stem cells plays a role in promoting a pro-inflammatory microenvironment, which supports the process of stem cell repair and self-renewal, leading to tumor recurrence." (PMID 34439871, 2021). "In the immune response, for example, TLR2 could enhance ovarian cancer stem cell self-renewal and eventually promote tumor repair and recurrence." (PMID 25907256, 2015). "TLR2 expression levels on monocytes has been shown to provide critical information when planning treatment against bacterial infectious diseases and filarial diseases, ovarian cancer, liver diseases, and bacterial infectious disease." (PMID 22815694, 2012). "Currently, our study demonstrates for the first time that activation of ovarian cancer patients’ neutrophils by ovarian cancer cells is dependent on the interaction of HspA1A originating from ovarian cancer cells, with TLR2 and TLR4 expressed on the surface of neutrophils." (PMID 22528050, 2012). "Therefore, we hypothesized that SAA1 released by ovarian cancer cells could recruit MDSCs and facilitate the differentiation of GMPs into MDSCs via TLR2/4 on MDSCs." (PMID 41029721, 2025). "In this study, we determined the expression of TLR2 in patients with ovarian cancer at various stages of the disease to demonstrate the utility of this receptor as a biomarker for advanced stage OC, which may help to improve the diagnosis process and thus increase survival in patients." (PMID 34439871, 2021).
ovarian carcinoma (continued). "With regards to the M1 markers, our data suggest a slight upregulation of IL-1β, IL-6, and TLR-2 expression in the presence of MSCs and reparixin, despite the fact that gene expression profiles reveal usually an M1/M2 mixed-polarization phenotype in ovarian cancer." (PMID 31504643, 2020). "Taken together, our research suggests that ovarian cancer cells secrete SAA1, which interacts with TLR2/4 on the surface of MDSCs, not only promoting MDSCs recruitment and GMP differentiation into MDSCs but also enhancing IL-1β secretion by MDSCs." (PMID 41029721, 2025). "Co-culture experiments further demonstrated that ovarian cancer cells recruit and activate MDSCs via SAA1 secretion, which engages TLR2/4 on MDSCs and induces IL-1β production." (PMID 41029721, 2025). "Our study reveals that SAA1 regulates IL-1β secretion by MDSCs through TLR2/4, while the secreted IL-1β in turn stimulates SAA1 production in ovarian cancer cells, thereby establishing a positive feedback loop between these components." (PMID 41029721, 2025). "In conclusion, ovarian cancer cells release SAA1, which acts on the TLR2/4 on the surface of MDSCs, thereby recruiting MDSCs and promoting the differentiation of GMPs into MDSCs." (PMID 41029721, 2025). "Different disease models have shown melatonin repressing pro-oxidant TLR2- and TLR4-mediated signaling cascades in the inflammatory phenotypes of ovarian cancer and coronary artery disease." (PMID 34356384, 2021). "We also observed a weak, but statistically significant correlation between T CD4+TLR2+ lymphocytes and HE4 serum concentration, which is a biomarker for ovarian cancer and until now was understood as a hormone-dependent factor." (PMID 32751735, 2020). "The participation of TLR2 and TLR4 expressed on neutrophils in the interaction via HspA1A with ovarian cancer cells was also investigated." (PMID 22528050, 2012). "We found that fMLP and PMA significantly increased the expression of both TLR2 and TLR4 on ovarian cancer patients’ neutrophils." (PMID 22528050, 2012). "In addition, it has been reported that healthy ovary tissue, human epithelial tumors and numerous ovarian cancer cell lines, including SKOV-3 cells, express TLR2, -3, -4 and -5 and IL-6 receptor." (PMID 28536612, 2016). "Whether or not the elevated expression is linked to any infection is not fully understood, but with no doubt, TLR2 may be a potential candidate to serve as a biomarker of ovarian cancer, especially in the early stage." (PMID 34439871, 2021).